DPP4 (dipeptidyl peptidase 4)
Diseases named in the same sentence as DPP4 in open-access papers (continued):
Sharing a sentence is not in itself a finding about the gene and the disease.
type 1 diabetes (continued). "The DPP4 inhibitor, such as linagliptin and alogliptin, can dramatically mitigate AGE and AGE receptor axis activity, thus alleviating the renal damage caused by inflammation, proteinuria, and oxidative stress in type 1 diabetes (T1DM) and T2DM." (PMID 36341356, 2022). "The objective of this study is to evaluate the effect of DPP-4 inhibitors, used as adjunct therapy with insulin, compared to placebo alongside insulin, on HbA1c, blood glucose levels, C-peptide levels, daily insulin dosage, BMI, weight change, and adverse events in patients with type 1 diabetes." (PMID 41026724, 2025). "It is considered that DPP-4 inhibitors affect neurite outgrowth of DRG neurons because they protect imperception and reduce intraepidermal nerve fiber density (IENFDs) in type 1 diabetic rodent models." (PMID 39201570, 2024). "Here we attempt to resolve that dilemma in part by reporting the first sufficiently powered study of adult-onset type 1 diabetes, including LADA, using dipeptidyl peptidase 4 (DPP-4) inhibitor and vitamin D as an adjunct to insulin and metformin." (PMID 37076476, 2023). "Inhibition of glucagon secretion may be involved in the efficacy of DPP-4 inhibitors for insulin-treated patients and inhibition of glucagon secretion as a GLP-1 receptor agonist may be important in type 1 diabetes." (PMID 26124906, 2015). "Moreover, DPP4 inhibitor reduced T-cell infiltration in islets, alleviated insulitis, and decreased the development of type 1 diabetes in nonobese diabetic mice." (PMID 38127960, 2024).
lung carcinoma (38 papers, 2015 to 2025). "TZD use in patients with greater DSCI [DSCI≧2, aHR 2.46 (1.25–4.82)] and DPP-4 inhibitors [aHR 2.24 (1.18–4.25)] had a higher risk of lung cancer." (PMID 34957135, 2021). "DPP4 inhibition in CRC and lung cancer is associated with improved OS, which possibly may be due to the effect of DPP4 inhibition on immunoregulation of cancer." (PMID 31124302, 2019). "Bishnoi and colleagues also found in lung cancer patients that the combined use of dipeptidyl peptidase 4 (DPP4) inhibitors and metformin can significantly increase survival." (PMID 41426321, 2025). "The use of DPP4 as a therapeutic target in immunotherapy was initially proposed based on in vitro studies using human KL lung cancer cell lines." (PMID 41283988, 2025). "Two DTP lung cancer cells with different proliferative capacities are established and identified dipeptidyl peptidase 4 (DPP4) as a potential therapeutic target." (PMID 40479551, 2025). "Analysis of the single‐cell dataset of osimertinib‐treated lung cancer patients also indicated higher expression of DPP4 in the residual cancer cells." (PMID 40479551, 2025). "The therapeutic potential of restoring DPP4 function to improve the immune response in KL lung cancer was evaluated using patient-derived tumor samples and syngeneic mouse models." (PMID 41283988, 2025). "In this study, we aimed to evaluate the therapeutic potential of restoring DPP4 function to improve the immune response in KL lung cancer using genomic analyses, patient-derived tumor samples, and syngeneic mouse models." (PMID 41283988, 2025). "Systematic genome analyses revealed that LKB1 loss suppresses dipeptidyl peptidase 4 (DPP4) expression and activity in KRAS-mutant lung cancer." (PMID 41283988, 2025). "CD26/DPP4 is a transmembrane glycoprotein, and studies have shown that lung cancer patients exhibit four times greater CD26/DPP4 activity than normal tissue." (PMID 38060494, 2023). "Whole RNA was extracted from lung cancer and normal lung tissues, and the expression levels of DPP4 and PSA were evaluated by means of quantitative polymerase chain reaction (qPCR)." (PMID 35650221, 2022). "Our siRNA, immunostaining and qPCR results indicated that not only DPP4 but also PSA is highly expressed in lung cancer cells." (PMID 35650221, 2022). "For instance, DPP4 plays a complicated role in lung cancer of different histologic types via interplay with other key molecules and immune regulation." (PMID 34955820, 2021). "Because of their controversial effects, further studies are needed to clarify the possible roles of DPP4 and DPP4 inhibitors in lung cancer." (PMID 34955820, 2021). "Previously, various forms of DPP4 were detected in human and placental plasma, as well as in lung cancer and normal tissues." (PMID 34178021, 2021). "Another study reported that DPP4 activity was high in human lung cancer tissue as well as in human and mouse lung adenocarcinoma cell lines." (PMID 34955820, 2021). "Further, our combined prognosis showed that the combined high expression of SP5, FOXP1, ROBO1, DPP4, CDYL2, and STAMBPL1 is associated to patients’ better clinical prognosis of patients with lung cancer." (PMID 32552834, 2020). "In lung cancer patients, DPP4 inhibitor only group (n = 419) showed HR of 0.93 (95% CI: 0.83‐1.03, P = 0.153) while the group with combined use of DPP4 inhibitors and metformin (n = 559) showed HR of 0.88 (95% CI: 0.80‐0.97, P = 0.010)." (PMID 31124302, 2019). "Subsequently, we examined DPP4 expression in KRAS-mutant lung cancer cell lines." (PMID 41283988, 2025). "We also examined DPP4 expression in tumor tissues from lung cancer patients by immunohistochemistry, and found that DPP4 was significantly upregulated in the residual tumor tissues after osimertinib treatment compared to the tumor tissues from patients who did not receive EGFR‐TKIs." (PMID 40479551, 2025).
lung carcinoma (continued). "Although DPP4 has been implicated in other malignancies, its specific role in KRAS-mutant lung cancer and association with ICI resistance remain unknown." (PMID 41283988, 2025). "Similarly, analysis of the SEER database indicates that DPP-4 inhibitors, which prevent the inactivation of endogenous GLP-1, are linked to improved survival in colon and lung cancers." (PMID 39001440, 2024). "The inhibition of CD26/DPP4 can suppress lung cancer growth in mice." (PMID 38060494, 2023). "Dipeptidyl peptidase 4 and puromycin-sensitive aminopeptidase were identified as enzymes mediating the cleavage and consequent fluorescence activation of QA-2OMeSiR, and it was confirmed that both enzymes are expressed in lung cancer." (PMID 35650221, 2022). "DPP4 expression and its role in lung cancer remains controversial." (PMID 34955820, 2021). "Diabetic patients with CRC or lung cancer who were treated with DPP4 inhibitors exhibited a statistically significant survival advantage (hazard ratio [HR] of 0.89; CI: 0.82‐0.97, P = 0.007) that remained significant after controlling for all other confounders." (PMID 31124302, 2019). "However, the roles of DPP4 on lung cancer remain controversial, due to the complex tumor microenvironment, and the variation tendency of its autoantibody may provide new strategies to study its specific functions." (PMID 39949782, 2025). "Thus, it is essential to explore the interaction of DPP4 with the tumor microenvironment, which may provide a new DPP4-targeted therapy strategy for lung cancer patients." (PMID 34955820, 2021). "However, DPP4 expression varies according to the different histologic subtypes of lung cancer." (PMID 34955820, 2021). "The cell surface marker DPP4 was significantly upregulated in the DTP and c‐DTP cells, as well as in the tumor tissues from lung cancer patients treated with EGFR‐TKIs." (PMID 40479551, 2025). "Knockdown of DPP4 and PSA (also known as aminopeptidase puromycin sensitive; NPEPPS) was performed in three different lung cancer cell lines: A549 (adenocarcinoma), H441 (highly differentiated adenocarcinoma), and H226 (squamous cell carcinoma)." (PMID 35650221, 2022). "Since ARV p17 has been proven to exert anti-carcinogenic activity on human lung cancer cells, amongst others, we wondered whether the viral protein could also be active on human microvascular endothelial cells of lung origin (HMVECs) and whether also in this case, its effects were mediated by DPP4." (PMID 33525607, 2021). "Supporting this concept, VbP (Talabostat; PT-100; BXCL-701), which exerts potent inhibition of DPP9 and DPP8 and moderate inhibition of DPP4 and FAP, has been shown to lessen tumor burden in lung cancer and sarcoma models." (PMID 33915844, 2021). "On analysis of individual cohorts of CRC and lung cancers, results were still statistically significant for the combined use of DPP4 inhibitors and metformin in CRC (HR 0.77) as well as for lung cancer (HR 0.88)." (PMID 31124302, 2019). "We conducted this Surveillance Epidemiology and Endpoint Research‐Medicare database study to evaluate the role of DPP4 inhibitors on the overall survival (OS) of diabetic patients diagnosed with colorectal (CRC) and lung cancers." (PMID 31124302, 2019). "For example, Jang and colleagues reported that DPP4 inhibition suppressed lung cancer growth via macrophage–NK-cell interactions, with increased DPP4 expression observed in patients with NSCLC, further highlighting the context-dependent roles of DPP4." (PMID 41283988, 2025).
lung carcinoma (continued). "Recent literature has established benefits of DPP4 inhibitors on progression-free survival (PFS) of diabetic patients with advanced colorectal and airway cancers, as well as improved overall survival (OS) in colorectal and lung cancer." (PMID 34055551, 2021). "The associations of three relatively new classes of anti-diabetic medications–glucagon-like peptide-1 receptor agonists (GLP-1RA), dipeptidyl peptidase 4 inhibitors (DPP-4I), and sodium-glucose cotransporter 2 inhibitors (SGLT-2I) with lung cancer prognosis remain unclear." (PMID 40040724, 2025). "Thus, although neither DPP4 nor PSA is expressed specifically in cancer cells, the combination may be more effective than either enzyme alone to detect lung cancer cells." (PMID 35650221, 2022).
thyroid cancer (38 papers, 2012 to 2026). "Another study implicated DPP-4 in the cell signaling axis of thyroid cancer metastasis; however, they were unable to see any beneficial effects of DPP-4 inhibition through sitagliptin." (PMID 38611003, 2024). "Regarding the effect on cancer metastasis, the co-prescription of metformin with DPP-4 inhibitors could prevent an elevated risk of thyroid cancer metastasis with DPP-4 inhibitor alone in T2DM patients." (PMID 34063285, 2021). "DPP4 enzyme activity also promotes cell migration and adhesion in cervical cancer lines, and its inhibition is associated with decreased invasion, migration, and colony formation capacity in thyroid cancer cells." (PMID 33143089, 2020). "In thyroid cancer α4β1 is stabilized by DPP4 (dipeptidyl peptidase-4), a multifunctional cell surface glycoprotein with a negative prognostic value, leading to epithelial-to-mesenchymal transition and to tumor metastasis." (PMID 37298541, 2023). "DPP4 facilitates epithelial-to-mesenchymal transformation and thyroid cancer cell metastasis by interacting with α4 and β1 integrin subunits to activate the transcription of the TGFB1 protein via the FAK/AKT/C-JUN/TGF-β signaling pathway." (PMID 37470034, 2023). "DPP4 (dipeptidyl peptidase 4) is expressed in many cancers, but the relationship between DPP4 and thyroid carcinoma (THCA) is incompletely understood." (PMID 36467461, 2022). "A cohort study in Korea represented that the DPP-4 inhibitor increases newly onset metastasis of primary thyroid cancer in diabetic patients." (PMID 34063285, 2021). "The pharmacological and genetic inhibition of DPP4 suppressed colony formation, cell migration, and invasion of thyroid cancer cells in vitro." (PMID 33498521, 2021). "As previous studies, DPP4 is highly expressed in thyroid cancer tissues, which has been considered as a prognostic factor." (PMID 33928101, 2021). "In more detail, a significant reduction of TMPRSS2 and CLEC4M in kidney and liver cancers, as well as a significant increase of DPP4 in thyroid cancer, was highlighted." (PMID 32970391, 2020). "DPP4 is overexpressed in thyroid cancer, and down-regulation inhibits cell growth and metastasis, indicating that DPP4 could be a risk factor, which contradicts Ting Lei's findings." (PMID 38586328, 2024). "Meta-analyses have found no increased risk of thyroid cancer in diabetic patients taking DPP-4 inhibitors." (PMID 38611003, 2024). "The role of DPP-4 inhibitors in thyroid cancer has recently gained popularity." (PMID 38611003, 2024). "We found that DPP4, TIMP1 and TYRO3 were associated with a better prognosis and survival in patients with thyroid cancer, while FABP4, NR4A1 and SNCA were associated with a poor prognosis and survival in patients with thyroid cancer." (PMID 36407322, 2022). "On the other hand, a propensity-matched cohort study of T2DM patients in Korea represented that DPP-4 inhibitor treatment did not increase the risk of pancreatic and thyroid cancer compared to metformin treatment." (PMID 34063285, 2021). "The AUC > 0.80 shown by TMPRSS2, CLEC4M and DPP4 suggests that these genes may act as effective molecular markers for kidney, liver and thyroid cancers." (PMID 32970391, 2020). "Therefore, the risk of thyroid cancer associated with incretin-based therapies is controversial and may differ between GLP-1R agonists and DPP-4 inhibitors or among different DPP-4 inhibitors." (PMID 27029076, 2016). "It has been recently reported that the KAT5 served as a transcriptional partner of FOSB to potentiate thyroid cancer growth and metastasis by enhancing FOSB-mediated transcriptional activation of DPP4." (PMID 39164746, 2024). "During follow-up, 76 patients with incident thyroid cancer were identified in the GLP1 receptor agonist group and 184 in the DPP4 inhibitor group; the incidence rates were 1.33 and 1.46 per 10 000 person years, respectively." (PMID 38683947, 2024).
thyroid cancer (continued). "Interestingly, we identified that the DPP4/CTNNB1/MET gene signature was overexpressed in PTCa, which, according to our analysis, is associated with immuno-invasive phenotypes, cancer progression, metastasis, resistance, and unfavorable clinical outcomes of thyroid cancer cohorts." (PMID 35205190, 2022). "A novel diagnostic test that measures the expression of a 3-gene signature (DPP4, SCG5 and CA12) has demonstrated promise in thyroid carcinoma assessment." (PMID 27776138, 2016). "Specifically, no statistically significant increase in thyroid cancer incidence was observed among patients treated with DPP-4 inhibitors, despite experimental data suggesting a potential risk." (PMID 39595655, 2024). "Among them, DPP4, GPX4, and GSS were protective factors for thyroid cancer prognosis." (PMID 33928101, 2021). "However, increased DPP4 expression was observed in LUAD, thyroid carcinoma, and uterine corpus endometrial carcinoma compared with adjacent normal tissues (P < 0.05; false discovery rate [FDR] < 0.05)." (PMID 33614513, 2021). "No case of thyroid cancer was observed for other DPP-4 inhibitors such as saxagliptin and linagliptin." (PMID 27029076, 2016). "Univariate cox regression analysis demonstrated that DPP4 [hazard ratio (HR): 0.756, 95% confidence interval (CI): 0.623–0.918, p = 0.004], GPX4 (HR: 0.381, 95% CI: 0.147–0.990, p = 0.048) and GSS (HR: 0.361, 95% CI: 0.139–0.935, p = 0.036) were protective factors for thyroid cancer prognosis." (PMID 33928101, 2021). "Our data suggested that AKR1C1 (p < 0.0001), DPP4 (p < 0.0001), GPX4 (p = 0.0001), GSS (p < 0.0001), HMGCR (p < 0.0001), TFRC (p < 0.0001), SQLE (p = 0.0004), and PGD (p = 0.0005) were all significantly highly expressed in thyroid cancer tissues compared to normal tissues." (PMID 33928101, 2021). "It has been shown in an in vivo study that TZD reduce serum DPP-4 activity as a result of reduced DPP-4 secretion and that DDP-4 is expressed in differentiated thyroid cancer cells but not in normal human thyrocytes." (PMID 26475035, 2015).
endothelial dysfunction (36 papers, 2013 to 2026). In vascular diseases, endothelial dysfunction is a systemic pathological state of the endothelium (the inner lining of blood vessels) and can be broadly defined as an imbalance between vasodilating and vasoconstricting substances produced by (or acting on) the endothelium. "Mechanisms underlying possible nephroprotective properties of DPP-4 inhibitors include reduction of oxidative stress and inflammation and improvement of endothelial dysfunction." (PMID 24089613, 2013). "In short, when endothelial dysfunction progresses to atherosclerosis and the risk of developing thromboembolism increases, DPP-4 inhibitors show beneficial effects there by suppressing macrophage infiltration, the formation of foam cells, and the proliferation of smooth muscle cells." (PMID 40771927, 2025). "Furthermore, the pharmacological inhibition of DPP4 is associated with attenuation of endothelial dysfunction and atherogenesis and also with reduction of inflammatory markers." (PMID 26146634, 2015). "Moreover, a recent clinical study indicated that endothelial dysfunction is closely associated with HFpEF, and thus favorable effects of DPP4 inhibitors on the vascular system suggest a therapeutic potential for preventing LV hypertrophy and HFpEF in humans." (PMID 24521405, 2014). "A previous study found that anagliptin, a dipeptidyl peptidase IV (DPP-4) inhibitor, suppresses IH by preventing endothelial dysfunction and regulating SOD-1/RhoA/Jun N-terminal kinase- (JNK-) mediated EC migration following balloon-induced injury." (PMID 35450412, 2022). "Because of this, gliptins potentially reduce the capacity of DPP4 to activate PAR2, with a beneficial effect on endothelial dysfunction, the main cellular mechanism predisposing to inflammation, typically occurring in the diabetic vasculature." (PMID 31956307, 2019). "Although improvement of endothelial dysfunction with a single administration of vildagliptin has been reported, in fact the reported short-term effects of treatment with DPP-4 inhibitors on FMD have been controversial." (PMID 29017497, 2017). "The present findings support the notion that DPP-4 plays a role in development of WD-induced aortic stiffening, vascular oxidative stress, endothelial dysfunction, and vascular remodeling." (PMID 27391040, 2016). "Many studies showed that DPP4 inhibition attenuated endothelial dysfunction, inflammation, and atherosclerotic process, but available phase IV studies did not associate the use of gliptins with reduced CV events in T2DM." (PMID 26146634, 2015). "It was demonstrated that a single administration of the DPP4 inhibitor vildagliptin was effective at ameliorating the postprandial endothelial dysfunction, accompanied by a reduction in the postprandial elevation of TG." (PMID 25452780, 2015). "The aim of the present study was to examine the postprandial effects of the dipeptidyl peptidase-4 inhibitor vildagliptin and the α-glucosidase inhibitor voglibose on endothelial dysfunction and lipid profiles following a single administration." (PMID 25452780, 2015). "In conclusion, we demonstrated that inhibition of DPP-4 with alogliptin was effective for reducing postprandial elevation of TG-rich lipoproteins and the accompanying induction of postprandial endothelial dysfunction." (PMID 23298374, 2013). "Linagliptin, a DPP4 inhibitor when added to insulin, metformin or both may improve endothelial dysfunction in a diabetic kidney disease (DKD) population." (PMID 32493344, 2020). "Moreover, soluble DPP4 can mediate endothelial dysfunction, acting via activation of PAR-2 and consequent release of prostanoids with vasoconstrictor properties." (PMID 31956307, 2019). "In this sense, DPP4 could also act as a direct mediator of endothelial dysfunction, via PAR2 activation and prostanoids release." (PMID 29325553, 2018).